NF1 (neurofibromin 1)
Diseases named in the same sentence as NF1 in open-access papers (continued):
Sharing a sentence is not in itself a finding about the gene and the disease.
tumor (continued). "While HSP90i enhances the sensitivity of tumor cells to MEKi by inhibiting compensatory signaling mechanisms, its application has rarely been extended to targeting NF1-associated pNFs." (PMID 40723243, 2025). "Small molecule inhibitors targeting MEK (selumetinib) and multiple tyrosine kinases (cabozantinib) have demonstrated clinical activity in tumor volume reduction and pain relief in patients with NF1-associated pNF." (PMID 41023593, 2025). "The NF1 tumor suppressor gene is recurrently mutated in human cancers and is associated with the neurofibromatosis type 1 (NF-1) cancer predisposition syndrome." (PMID 40587782, 2025). "The NCI-MATCH trial evaluated the efficacy of trametinib in patients with advanced neoplasia carrying an NF1 mutation within one of its sub-protocols." (PMID 41170454, 2025). "The kinase signaling cluster (Cluster‐2) is associated with genes such as RET and NF1, which are related to higher tumor differentiation, lower malignant potential, and better prognosis." (PMID 40196048, 2025). "As discussed later, combination therapies targeting both mTOR and MEK pathways are now being investigated for some NF1-associated tumor types." (PMID 41294711, 2025). "These mutations were detected in 92% of sporadic tumours, 70% of NF1-associated tumours, and 90% of radiotherapy-associated tumours." (PMID 40843672, 2025). "Further evaluation of the tumor by Caris Molecular Intelligence revealed several mutations, including the NF1 variant of uncertain significance (VUS), NRAS, PBRM1, FAT1, TERT Promoter, and ATM." (PMID 40125165, 2025). "We assess the predictive value of MRI-based, three-dimensionally assessed tumor burden and growth velocity for VA outcomes in NF1-associated and sporadic OPGs." (PMID 40643687, 2025). "An analysis of 15 MPNSTs from 12 patients, including 6 NF1-associated tumours, 4 sporadic tumours, 4 radiotherapy-associated tumours, and 1 epithelioid MPNST, was conducted." (PMID 40843672, 2025). "Neurofibromin, the protein encoded by the NF1 gene, functions as a tumor suppressor and regulator of cellular proliferation through its role as a GTPase-activating protein." (PMID 41487738, 2025). "A newly published study provides important insight, showing that loss of the NF1/neurofibromin tumor suppressor confers greater sensitivity to CDK4/6 inhibition, as these tumors rely heavily on CDK4/6 activity for survival under endocrine therapy." (PMID 41226361, 2025). "Case 6, which had the highest number of SNVs, had missense mutations in ATM, POLE and BRCA2, as well as known pathogenic mutations from ClinVar in MSH6, RAD50, APC and NF1, likely explaining the high mutational load in this tumor." (PMID 40670673, 2025). "Early preclinical studies using oHSV G47Δ in NF1-associated MPNST models have demonstrated significantly inhibited tumor growth and prolonged survival." (PMID 41374990, 2025). "NF1 is caused by dominant loss-of-function pathogenic variants (PVs) of the tumour-suppressor gene NF1, which encodes neurofibromin, a negative regulator of rat sarcoma proteins." (PMID 40759488, 2025).
tumor (continued). "While the clinical and family history support the diagnosis of NF1, definitive proof of NF1-driven tumorigenesis would require genetic confirmation of a germline NF1 pathogenic variant and demonstration of biallelic inactivation in the tumor." (PMID 41216086, 2025). "Although individuals with NF1 inherit a germline variant in one NF1 allele, a single mutated copy is insufficient for tumor formation." (PMID 41463204, 2025). "NF1 is a complex genetic disorder inherited in an autosomal dominant manner caused by germline mutations in the NF1 tumour suppressor gene located on chromosome 17q11.2." (PMID 40843672, 2025). "Our current data confirm that these tumour suppressors are frequently disrupted by structural alterations, with pathogenic genomic events of any kind seen in 15% (NF1), 14% (PTEN) and 14% (RB1) of samples." (PMID 40593568, 2025). "We collected data from 63 patients from our molecular tumor board for NF1 gene sequencing and detected 72 NF1 variants, thereby 32% of those being pathogenic." (PMID 41220108, 2025). "Further data reporting with increasing granularity is needed to elucidate a potential association between NF2, NF1 and seizure activity or tumor grade in PM." (PMID 40637916, 2025). "We also summarize the major preclinical and clinical advances in NF1-associated tumor therapy, including AAV-based gene delivery, oHSV approaches, CAR T-cell strategies, and small-molecule and pathway-targeted inhibitors." (PMID 41374990, 2025). "The effect of CQ was also conserved in a Drosophila NF1 in vivo model and in a xenografted NF1‐deficient tumor cell line grown in mice, with CQ treatment resulting in a more significant reduction in tumor growth than selumetinib treatment." (PMID 39129390, 2025). "MEKi reduces tumor volume and improves symptoms in the majority of patients with NF1-associated pNF, the precursor to MPNST." (PMID 41023593, 2025). "Beyond targeted inhibitors, mebendazole has shown chemopreventive effects against malignant transformation in NF1-associated tumor models, accompanied by reduced RAS activity." (PMID 41374990, 2025). "Tumour suppressor gene defect can result in NF-1, and it will predispose the individual to malignancy." (PMID 40230769, 2025). "NF1 presents unique, complex challenges in tumor management due to its diverse tumor types and underlying molecular heterogeneity." (PMID 41294711, 2025). "In vitro analyses also showed that tranilast suppressed expression of mesenchymal markers and angiogenesis-related genes, suggesting its potential to inhibit NF1-associated tumor growth through EMT and angiogenesis suppression." (PMID 41294711, 2025). "The 2023 European Reference Network on Genetic Tumor Risk Syndromes (ERN GENTURIS) tumor surveillance guidelines for individuals with NF1 provide a valuable, evidence-based decision-making resource for physicians treating patients with NF1." (PMID 39264447, 2025). "Expanding the understanding of the involvement of microRNA in MPNST pathogenesis, miR-10b has also been identified as a key regulator in NF1-associated tumour progression and prognosis." (PMID 40843672, 2025). "Genetic testing indicated multiple tumor-specific mutations including whole-chromosome losses (3, 6, 10, 11, 13, 14, 17, 18, 21, and X) and point mutations inTP53,NF1, andPTEN.Germline mutation testing was within normal limits, including normalTSC1/TSC2." (PMID 40018440, 2025). "Trametinib had only limited clinical efficacy in other tumor types with NF1 mutations in the NCI-Match trial." (PMID 41170454, 2025).
tumor (continued). "In 10 of these 29 patients, somatic mutations were detected: six tumours with a somatic mutation in the NF1-gene, and two patients each with mutations in the EPAS1- and the VHL-gene." (PMID 41276740, 2025). "The NF1 gene, located on chromosome 17, encodes neurofibromin, a protein that acts as a tumor suppressor by regulating cell growth." (PMID 40764996, 2025). "In summary, the transition from NF1 to MPNSTs is influenced by multiple genetic mutations and disrupted signaling pathways, alongside an altered tumor microenvironment, highlighting the complexity of its pathogenesis." (PMID 40182390, 2025). "NF-1 is a tumor suppressor gene and encodes for neurofibromin, a protein responsible for regulating cellular growth and differentiation." (PMID 40416267, 2025). "Functional genomic screening in NF1-mutant tumor cells reveals NF2 loss and PAK activation underlie selumetinib resistance, and we find that concurrent MEK and PAK inhibition is effective in vivo." (PMID 38216572, 2024). "The NF1 tumor suppressor gene encodes the NF1-protein, which is Ras GTPase-activating (RasGAP) and thereby inactivating RAS." (PMID 39466488, 2024). "Overall, these results show that the IF/+ indel in one Nf1 allele causes the gene expression profile of mature adipocytes before tumor formation to mimic a preadipocyte- and fibroblast-like cell state." (PMID 38799507, 2024). "Genomic analysis of HGAP tumours has demonstrated a propensity for somatic MAPK pathway activation with NF1 variants being the most common followed by FGFR15,12." (PMID 39427038, 2024). "NF1 is inherited in an autosomal dominant manner and is caused by loss-of-function variants in the NF1 tumor suppression gene situated on 17q11.2." (PMID 38281202, 2024). "The NF1 gene functions as a tumor suppressor, and mutations in this gene lead to endothelial and pericyte cell proliferation, which increases the angiogenic response to ischemia." (PMID 39759687, 2024). "As an autosomal dominant condition, it involves mutations in the neurofibromatosis type 1 (NF1) tumor-suppressor gene, inherited in a recessive manner." (PMID 39211690, 2024). "NF1 is attributed to mutations in the NF1-gene, located on chromosome 17q11.2, a tumor-suppressor gene involved in RAS-MAPK (mitogen-activated protein kinase) signaling." (PMID 39211378, 2024). "Peripheral nerve tumors caused by loss of the NF1 tumor suppressor provide a unique system in which to study the roles of the tumor microenvironment in the formation of benign tumor growth." (PMID 38458648, 2024). "RGNT-1 was a secondary tumour with NF1 mutation, whose first diagnosis was haemangioma 6 years ago, and all other RGNTs were primary cases." (PMID 38764775, 2024). "It was immunoreactive in one tumor with an NF1 truncating mutation that was distal to the antibody recognition site." (PMID 39472976, 2024). "NF1 mutations are the main ‘driver’ mutation in amelanotic and desmoplastic MM in which the tumour cells have a spindle cell morphology consistent with a more aggressive phenotype." (PMID 39355740, 2024). "Deficiency of tumor suppressors such as Nf1 is usually associated with increased cell proliferation." (PMID 38360927, 2024). "The other three sporadic tumor features distanced them further from classic MPNSTs: SP‐01 only has NF1 mutated, and SP‐05 and SP‐06 have only CDKN2A inactivated." (PMID 37798904, 2024). "ANNUBP is an NF1-associated tumor with the histologic features of nuclear atypia, hypercellularity, and increased mitotic activity." (PMID 39594712, 2024).
tumor (continued). "Preoperative tumor volumes were significantly (p = 0.048) higher in NF1-associated tumors (mean volume 299.1 cm3) compared with sporadic cases (mean volume 17.8 cm3)." (PMID 39594712, 2024). "Although only 1% of GBM tumours exhibit RAS mutation or amplification, 10% of GBM tumours contain inactivating genetic alterations of neurofibromin 1 (NF1) that lead to hyperactive RAS activity by enhancing intrinsic GTPase activity." (PMID 38637419, 2024). "This indicates that collagen and matrix changes correspond to Nf1 loss of function and rates of tumor onset." (PMID 38799507, 2024). "In this study, we found that IFITM1 was downregulated in MPNST tumor tissue samples from patients with NF1 and NF1-associated MPNST Schwann cell lines." (PMID 39273214, 2024). "Stem-like tumor cells have been reported to promote tumor progression and drug resistance in NF1-associated tumors." (PMID 39518076, 2024). "Loss of heterozygosity (LOH) through partial or complete chromosomal deletion typically occurs in individuals with NF1 when the remaining allele is loss in tumour cells, leading to complete loss of neurofibromin function." (PMID 39409887, 2024). "This case report illustrates a case of NF-1-associated bladder ganglioneuroma, which demonstrated an interval reduction in tumor size and resolution of urinary and bowel symptoms after starting trametinib." (PMID 39070150, 2024). "The most crucial question is why AMT only observed in mature adipocytes from Nf1-deficient IF/+ that have the slowest tumor onset (compared to PS-20/+ and IF; PS-21/+ Nf1-deficient lines)." (PMID 38799507, 2024). "The NF1 gene encodes for the protein neurofibromin, a tumor suppressor that negatively regulates the p21Ras GTPase." (PMID 38913608, 2024). "Tumor mutational burden was significantly higher in NF1 mutant tumors (median 70.2 mutations/Mb) and co-mutated tumors (median 66.5 mutations/Mb) (p < 0.001, one-way ANOVA) compared with other TCGA driver genes." (PMID 38611025, 2024). "Magnetic resonance imaging (MRI) with diffusion-weighted imaging is the gold standard imaging technique for long-term monitoring of NF1-associated tumours due to its excellent soft tissue contrast." (PMID 39729173, 2024). "The loss of two bona fide MAPK pathway tumor suppressors conferred resistance to VT107: NF1, which functions in the upstream part of the signal transduction pathway; and CIC, a transcription repressor." (PMID 39103676, 2024). "In the central nervous system (CNS), mouse Nf1 optic gliomas require the elaboration of Ccl5 from tumor-associated monocytes (TAMs)." (PMID 38308315, 2024). "A previous report detailed 10 cases of metastatic pheochromocytoma associated with NF1, with a median age of 46 years and median tumor size of 6 cm." (PMID 38966763, 2024). "Among MM drivers, somatic mutations of NRAS and the TERT promoter are reported, as well as mutually exclusive loss of function mutation of the tumor suppressors NF1 and SPRED1, the latter co-occurring with activating KIT mutations." (PMID 38191367, 2024). "NF1 tumor formation is initiated by the loss of contact between the SC and the axon beginning the process of tumor formation." (PMID 39110684, 2024). "The findings in the study demonstrate that Nf1-deficient rats with the earliest tumor onset have a significant increase in collagen expression compared to the Nf1-deficient rats with later tumor onset." (PMID 38799507, 2024). "For example, NF1 microdeletion syndrome and missense variants in codons 844–848 have been linked to more severe phenotypes, as well as a greater tumor burden and increased risk of malignancy." (PMID 39592598, 2024).
tumor (continued). "The results of these transplantation experiments indicated that an Nf1-deficient mammary stroma was necessary to promote tumor growth and progression." (PMID 38799507, 2024). "We identified increased collagen content in Nf1-deficient rat mammary glands before tumor formation that correlated with age of tumor onset." (PMID 38799507, 2024). "Lastly, pain intensity improved in 78% (n = 18)/33% (n = 4), was maintained in 22% (n = 5)/67% (n = 8), and worsened in 0% of NF1-associated/SPO tumor cases." (PMID 39594712, 2024). "The NF1 gene, located on chromosome 17q11.2, plays a crucial role in tumor suppression, and pathogenic variants in this gene lead to the development of NF14." (PMID 39592598, 2024). "At present, it is not sufficiently clear to what extent diffusion-weighted imaging can be regarded as an equivalent method to discriminate NF1-associated tumours with suspected malignant transformation in routine clinical practice." (PMID 39729173, 2024). "NF1‐associated mutations are the most studied mutation in low grade tumours and it is one of the most studied through clinical trials." (PMID 38299304, 2024). "It is a characteristic feature of NF1, an autosomal dominant disorder caused by a mutation in the NF1 tumor suppressor gene located on chromosome 17 at locus 17q11.2." (PMID 38903359, 2024). "In our study, we investigated the impact of Nf1 loss of function on the mammary stroma before tumor formation." (PMID 38799507, 2024). "Several tumors harboring genomic alterations with US Food and Drug Administration-approved indications in other tumor types were found including NF1, PIK3CA, EGFR Exon 19/20 insertions, and BRAF V600E mutations." (PMID 39191445, 2024). "As a variant in a tumor-suppressing gene, it seems to follow the two-hit theory, as tumors associated with NF1 show a loss of heterozygosity." (PMID 38893137, 2024). "Proper diagnosis of abdominal manifestations of NF-1 is essential to finding appropriate treatment and preventing severe organic complications associated with tumor masses." (PMID 39403336, 2024). "The imaging procedure was used to specify tumor localization and treatment needs of a group of patients suffering from specific tumors preferentially arising in NF1, a tumor predisposition syndrome." (PMID 37173460, 2024). "Genetically engineered mice that carry a homozygous deletion of Nf1 in SCs and SC precursors (SCPs) causes spontaneous tumor formation over time and have become an essential tool to study NF1 tumorigenesis." (PMID 38258905, 2024). "As such, to study the impact of CAP on NF1-associated tumor cell death, we first evaluated cell death in vitro at different CAP exposure times at 10, 30, 60, 90, and 180 s, utilizing dCAP and iCAP." (PMID 39335500, 2024). "Loss of nuclear H3K27me3 is present in HG sporadic and radiation-induced tumours but lacks sensitivity in NF1-associated tumours." (PMID 39409887, 2024). "Mesenchymal GBMs are characterized by a high frequency of NF1 mutations, tumor necrosis, a complex tumor microenvironment, and a poorer prognosis." (PMID 37545464, 2024). "Neurofibromatosis‐1 (NF‐1) is a genetic disease caused by mutations in the NF‐1 tumor suppressor gene." (PMID 38769783, 2024). "Nf1 plays a crucial role in the nervous system beyond cognition and physiology, as human-derived Nf1 mutations increase neuronal excitability in mice, accelerating tumor progression in the central and peripheral nervous system." (PMID 39217323, 2024). "NF-1 gene mutations result in the absence or reduced function of neurofibromin protein, thereby promoting tumor development and other clinical findings." (PMID 38380111, 2024). "NF1 is a tumor suppressor gene that encodes a protein called neurofibromin, which regulates the RAS pathway." (PMID 38493052, 2024). "Genetic or pharmacological inhibiting neutrophils in HCC or monocyte-deficient PDGFB-driven and Nf1-silenced GBM models extend the survival of tumor-bearing mice." (PMID 37012245, 2023).